HOXB9 (homeobox B9)
Diseases named in the same sentence as HOXB9 in open-access papers (continued):
Sharing a sentence is not in itself a finding about the gene and the disease.
glioma (8 papers, 2019 to 2025). A benign or malignant brain and spinal cord tumor that arises from glial cells (astrocytes, oligodendrocytes, ependymal cells). "WB analysis revealed that, compared with those in normal glial cells, the contents of EGR1 and HOXB9 in glioma cells obviously increased (0.690 ± 0.024 vs. 0.124 ± 0.008, 0.719 ± 0.007 vs. 0.114 ± 0.015; *p < 0.05)." (PMID 40936205, 2025). "The combined effect of TMZ-A2SLN and small-interfering RNA (siRNA) that can knock down the expression of the HOXB9 gene (siHOXB9) augmented the sensitivity of the glioma cell line U251 to TMZ." (PMID 41515958, 2025). "Last, our in vitro experiments revealed that reducing the expression of HOXB9 significantly inhibited the proliferation and invasive ability of glioma cells." (PMID 37301547, 2023). "Previous studies have shown that in gliomas, HOXB9 can directly bind to the promoter of TGF-β1 to induce TGF-β1 expression." (PMID 36158877, 2022). "Conversely, other transcripts, such as HOXA‐AS3, HOXB‐AS3 and HOXB9, were upregulated only in approximately 20% of IDHwt glioma samples." (PMID 33720519, 2021). "Conversely, expression data from the cancer cell line encyclopaedia database (CCLE) showed widespread repression of EMX2 in a large panel of glioma cell lines, whilst aberrant expression of HOXB9 was detected in 19 lines (RPKM ≥ 5)." (PMID 31468686, 2019). "The results of this study revealed that the miR‐192‐EGR1/HOXB9 loop might be involved in the regulation of glioma interstitial transformation, which was consistent with changes in glioma cell stemness." (PMID 40936205, 2025). "This regulatory factor could inhibit the expression of downstream EGR1 and HOXB9 through targeted binding, thus forming a semi‐open loop that could regulate the malignant phenotypes of glioma." (PMID 40936205, 2025). "Our research revealed that both EGR1 and HOXB9 promote MT in glioma cells." (PMID 40936205, 2025). "Immunohistochemical staining of isolated glioma samples revealed that, compared with those in the NC group, EGR1 and HOXB9 protein levels in glioma samples from the OE miR‐192 group were obviously lower (U87 group: 0.35 ± 0.07 vs. 1.10 ± 0.14; U251 group: 0.40 ± 0.14 vs. 1.25 ± 0.07; *p < 0.05)." (PMID 40936205, 2025). "The overexpression of HOXB9 could increase the stemness of glioma cells, thus increasing chemotherapy resistance in these cases." (PMID 40936205, 2025). "Experiments further revealed that knockdown of HOXB9 expression could suppress proliferation, migration, and invasion of glioma cells." (PMID 37301547, 2023). "Interference with HOXB9 could inhibit the stem properties of glioma cells." (PMID 40936205, 2025). "Furthermore, HOXB9 was confirmed to be a potent oncogene in glioma cell line experiment." (PMID 37301547, 2023). "A cell model test revealed that in glioma cells overexpressing miR‐192, the protein levels of EGR1 and HOXB9 were significantly lower (EGR1: 0.217 ± 0.010 vs. 0.710 ± 0.041; HOXB9: 0.419 ± 0.004 vs. 0.794 ± 0.064; * p < 0.05)." (PMID 40936205, 2025). "Compared with those in normal control cells, the immunofluorescence signals of EGR1 and HOXB9 were obviously lower in glioma cells overexpressing miR‐192 (EGR1: 7.40 ± 0.79 vs. 28.35 ± 1.56; HOXB9: 10.75 ± 1.19 vs. 30.37 ± 2.28; *p < 0.05)." (PMID 40936205, 2025). "MiR‐192 was significantly reduced in glioma samples, and this factor downregulated EGR1 and HOXB9 via targeted binding, thus forming a semi‐open loop." (PMID 40936205, 2025). "Similarly, compared with those in low‐grade glioma samples (WHO I–II), EGR1 and HOXB9 levels were also significantly increased in high‐grade (WHO III–IV) glioma samples (0.463 ± 0.026 vs. 0.249 ± 0.013, 0.543 ± 0.018 vs. 0.233 ± 0.015; *p < 0.05)." (PMID 40936205, 2025).
glioma (continued). "Moreover, HOXB9 may play a crucial regulatory role in the PPAR signaling pathway, the neural signaling pathway, the phospholipase D signaling pathway, the IL-17 signaling pathway, mineral absorption, and other pathways during glioma cell treatment." (PMID 41515958, 2025).
colorectal cancer (7 papers, 2014 to 2023). A primary or metastatic malignant neoplasm that affects the colon or rectum. "It is reported that Homeobox B9 is overexpressed in liver cancer and colorectal cancer and promotes tumor cell progression." (PMID 37301547, 2023). "Colorectal cancer patients with HOXB9 overexpression had poor overall survival in this study, but conversely demonstrated better overall survival with bevacizumab treatment." (PMID 24885802, 2014). "HOXB9 is also expressed in colorectal cancer and functions as a strong tumorigenic factor through activation of the TGF-beta axis and angiogenesis." (PMID 24885802, 2014). "We also examined the effect of HOXB9 overexpression in colorectal cancer using a proliferation assay, ELISA, a multiplex assay, and xenograft models." (PMID 24885802, 2014). "We examined the expression of HOXB9 in colorectal cancer using qPCR and in situ hybridization." (PMID 24885802, 2014). "In the present study, we demonstrated that HOXB9 also promoted the expression of angiogenic factors and TGF-beta ligands in colorectal cancer." (PMID 24885802, 2014). "To investigate HOXB9 expression in colorectal cancer, we examined specimens from patients who had p-stage II or III colorectal cancer and had undergone surgery at our institute." (PMID 24885802, 2014).
colon adenocarcinoma (6 papers, 2018 to 2023). "For example, elevated HOXB9 expression predicts a favorable outcome in colon adenocarcinoma patients." (PMID 34445617, 2021).
melanoma (5 papers, 2020 to 2025). A malignant, usually aggressive tumor composed of atypical, neoplastic melanocytes. "Our data are supported by findings in osteosarcoma and melanoma, showing that HOXB9 and PBX1, respectively, contribute to SPP1 activation in these tumours." (PMID 40149711, 2025). "Additionally, miR-122-5p can act as an anti-melanoma cofactor of brusatol, reducing the expression of the transcription factor HOXB9." (PMID 39790031, 2025). "In the GSE91061 melanoma cohort, the relationship between HOXB9 expression and response to anti-PD-1 therapy in melanoma patients suggests that individuals with low HOXB9 expression had better survival rates and longer survival times compared to those with high HOXB9 expression." (PMID 37301547, 2023). "Further, in the Gide2019 melanoma cohort, the response rate to anti-CTLA- 4/anti-PD-1 therapy was 25% in high-HOXB9 expression patients, significantly lower than 71.4% in low-HOXB9 expression patients." (PMID 37301547, 2023). "The promoter of miR-765 binds directly to HOXB9, promotes self-transcription and then targets FOXA2 to regulate FOXA2, resulting in a decrease in FOXA2 and an increase in melanoma tumor stem cells." (PMID 33313406, 2020). "This reduction decreases HOXB9’s binding to the SCD1 promoter, enhancing the anti-melanoma effect." (PMID 39790031, 2025). "Similarly, Homeobox B9 (HOXB9) regulates the self-renewal of CSCs and antagonizes ER stress-induced apoptosis by modulating the miR–765–FOXA2 axis in melanoma cells." (PMID 36890838, 2023).
lymph node metastasis (4 papers, 2015 to 2020). "Studies have also shown that the expression of HOXB9 in EC is increased, and is related to histological grade and lymph node metastasis." (PMID 33041670, 2020). "Correlation was shown between PD-L1 and tumor size and lymph node metastasis, HOXB9 and tumor size, BLNK and perineural invasion, and between ZNF813 and perineural invasion." (PMID 26041877, 2015). "HOXB9 expression significantly decreased in adenocarcinomas with a tumor size larger than 5 cm or with lymph node metastasis or at a late TNM stages (stage III or IV)." (PMID 26536658, 2015). "In addition, HOXB9 expression notably correlated with histological grade and lymph node metastasis status." (PMID 29724991, 2018). "Furthermore, reduced HOXB9 expression was also observed in patients with lymph node metastasis relative to those without metastasis (P = 0.005)." (PMID 26536658, 2015).
ovarian carcinoma (4 papers, 2015 to 2023). A malignant neoplasm originating from the surface ovarian epithelium. "The purpose of this study was to identify the role of HOXB9 and associated molecular mechanism in acquiring chemoresistance to ovarian cancer cells." (PMID 36674764, 2023). "Another study from the TCGA that analyzed HOX gene data reported that high expression of HOXB9 was significantly associated with suboptimal residual disease after debulking surgery, which is one of the most important and poor prognostic factors in ovarian cancer." (PMID 36674764, 2023). "Our data suggest that HOXB9 overexpression may cause chemoresistance in ovarian cancer cells by differential induction of ERCC-1, MRP-2, and XIAP depending on the strength of HOXB9 expression through inhibition of the mitochondrial pathway of apoptosis, including Bax/Bcl-2." (PMID 36674764, 2023). "The strength of this study is that we first identified the function of HOXB9 in conferring chemoresistance to ovarian cancer cells and its mechanism using HOXB9-overexpressing ovarian cancer cells and a mouse xenograft model." (PMID 36674764, 2023). "In this study, we investigated the function of HOXB9 in the chemoresistance of ovarian cancer cells and its molecular mechanism using HOXB9-overexpressing SKOV3 cells and a mouse xenograft model." (PMID 36674764, 2023). "To explore the correlation between HOXB9 and cisplatin resistance in ovarian cancer cells, we performed a Presto Blue assay to evaluate the effect of HOXB9 overexpression on cisplatin-induced apoptotic cell death." (PMID 36674764, 2023). "Although there are limited data on the role of HOXB9 in ovarian cancer in the literature, our findings are consistent with the results of the existing studies." (PMID 36674764, 2023). "Inhibiting HOXB9 overexpression in RMUG‐S cells can effectively kill platinum‐resistant ovarian cancer cells by facilitating apoptosis and inhibiting EMT." (PMID 31970886, 2020). "The downregulation of EGR1 and HOXB9 by miR-192 was further confirmed in another ovarian cancer cell line, HeyA8." (PMID 27041221, 2016). "Considering the importance of the regulation of TGF-β pathway by homeodomain proteins including HOXB9 in promoting tumorigenesis, we investigated the possible association of PITX2 and TGF-β signalling in ovarian cancer." (PMID 26298390, 2015). "Although the function of HOX genes in ovarian cancer remains unclear, HOXB9 is known to have multiple roles in tumor growth, angiogenesis, chemoresistance, as well as immune evasion as a suppressor of activated human T cells in cancer." (PMID 36674764, 2023). "Inhibiting HOXB9 overexpression in RMUG‐S cells may effectively eliminate platinum‐resistant ovarian cancer cells by facilitating apoptosis and inhibiting EMT." (PMID 31970886, 2020). "In conclusion, the platinum resistance of SKOV3 ovarian cancer cells may be different in terms of its refractoriness to cisplatin treatment according to the level of HOXB9 overexpression and the subsequently induced expression of ERCC-1, MRP-2, and XIAP, as well as Bcl-2/Bax expression." (PMID 36674764, 2023). "We demonstrated that platinum resistance, which is mediated by cisplatin-induced ERCC-1, MRP-2, and XIAP in SKOV3 ovarian cancer cells (with a moderate level of HOXB9 expression), could be overcome by cisplatin treatment alone through the inhibition of Bcl-2 and activation of Bax." (PMID 36674764, 2023). "After establishing HOXB9-overexpressing cells (HOXB9-OE/SKOV3), cisplatin resistance-induced cells (Cis-R/SKOV3), and an ovarian cancer xenograft mouse model, the effects of HOXB9 were evaluated in vitro and in vivo." (PMID 36674764, 2023). "Similar to ovarian cancer, miR-192 treatment mediated a robust downregulation of EGR1 and HOXB9 levels and significant decreases in several angiogenic factors including IL6, IL8 and EFNA1; consistent with the pattern observed after siEGR1/siHOXB9 treatment." (PMID 27041221, 2016).
pancreatic ductal adenocarcinoma (4 papers, 2018 to 2023). An infiltrating adenocarcinoma that arises from the epithelial cells of the pancreas. "HOXB9 controls erythroblastic leukemia viral oncogene homolog (ErbB), TGFb pathway, and angiogenic factor, resulting in EMT, as well as tumor proliferation and chemoresistance; however, little is known about the expression of HOXB9 in pancreatic ductal adenocarcinoma (PDAC)." (PMID 35634239, 2022).
adrenocortical carcinoma (3 papers, 2021 to 2023). "For example, higher HOXB9 expression was associated with poorer prognosis in adrenocortical carcinoma and simultaneous overexpression of HOXB9 and Ctnnb1 in adrenal cortex of transgenic mice led to larger adrenal tumors." (PMID 36387262, 2022). "Consistent with our mouse studies, overexpression of HOXB9 in the human adrenal cortical tumour cell line H295R led to a small but significant increase in cell number." (PMID 33214683, 2021).
metastatic disease (3 papers, 2015 to 2022). "High HOXB9 expression was found to be associated with a significant risk for metastatic disease (OR 4.14, 95% CI: 1.64–10.43, p = 0.003)." (PMID 34948228, 2021). "Our post-hoc meta-analysis identified that HOXB9 was significantly associated with the presence of metastatic disease." (PMID 34948228, 2021). "HOXB9 protein overexpression was identified to be associated with the presence of metastatic disease indicating that it may be a critical transcription factor in CRC." (PMID 34948228, 2021). "HOXB9 was the most frequently investigated protein and from our post-hoc meta-analysis, we found that HOXB9 high expression was associated with an increased risk for metastatic disease indicating that it may predispose to worse OS." (PMID 34948228, 2021). "Collectively, these results indicate that HOXB9 and GalNAc-T14 expression are strongly correlated with metastatic tumor formation." (PMID 26544896, 2015).
Obesity (3 papers, 2023 to 2025). Accumulation of substantial excess body fat. "DNA methylation levels at CpG sites in or close to HOXB9 have been found to be associated with epigenetic ageing of liver tissue, a process that was previously found to be accelerated by obesity." (PMID 38198623, 2024). "The HOXB9 expression level was the highest in the extreme obese group, which also coincided with obesity as a high-risk factor for EC." (PMID 36803556, 2023). "However, among patients with high HOXB9 expression, patients with obesity had a worse prognosis than normal-weight patients (HR = 1.87; p = 0.04), suggesting that obesity is associated with poor prognosis." (PMID 41402312, 2025).
osteosarcoma (3 papers, 2021 to 2025). A usually aggressive malignant bone-forming mesenchymal neoplasm, predominantly affecting adolescents and young adults. "Downregulation of FAT10 expression suppresses the invasive and migratory abilities of osteosarcoma cells, potentially through its positive regulation of β-catenin and HOXB9 expression to promote osteosarcoma development." (PMID 39062505, 2024). "Their study found that hsa-miR-557 could inhibit the malignant behavior of osteosarcoma by reducing HOXB9, which can deactivate the epithelial-mesenchymal transition (EMT) process." (PMID 35087570, 2021).
adrenal tumors (2 papers, 2021 to 2022). "Transgenic overexpression of Hoxb9 in the adrenal cortex of mice with activated Ctnnb1 led to larger adrenal tumours." (PMID 33214683, 2021). "Adrenal tumours from double-mutant mice expressed higher levels of Hoxb9 mRNA and protein than single Ctnnb1 mutants, confirming expression of the transgene." (PMID 33214683, 2021). "We used transgenic mouse models to determine the role of Hoxb9 in adrenal tumour development." (PMID 33214683, 2021).
atherosclerosis (2 papers, 2020 to 2025). A disease characterized by the build-up of fatty material and calcium deposition in the arterial wall resulting in partial or complete occlusion of the arterial lumen. "Interestingly, HoxB9 negatively regulates the expression of IL-1β which can have both protective and pathogenic effects in atherosclerosis." (PMID 31504243, 2020). "HOXA5 safeguards against atherosclerosis via peroxisome proliferator-activated receptor gamma (PPARγ), whereas HOXB9 exacerbates inflammation through bone morphogenetic protein 4-tumor necrosis factor (BMP4-TNF)." (PMID 41181801, 2025). "HoxB9 is of considerable interest because it is highly abundant at the atheroprone region of the aorta and it drives two processes that promote atherosclerosis; inflammation and proliferation." (PMID 31504243, 2020). "We focused our studies on HoxB9 because inhibiting this Hox gene could be particularly effective in treating atherosclerosis since it drives two distinct pathophysiological functions, inflammation and proliferation." (PMID 31504243, 2020).
breast tumors (2 papers, 2015 to 2021). "In breast tumors, the expression of HOXB9 was upregulated, which induced the factors associated with the fate of tumor cells promoting the progression and metastasis of the disease." (PMID 34055607, 2021).
glioblastoma (2 papers, 2023 to 2025). The most malignant astrocytic tumor (WHO grade IV). "The HOXB9 gene shows elevated expression in patients with high-grade glioblastoma (GBM) and is associated with multiple drug-resistant mechanisms, including MGMT and P-gp." (PMID 41515958, 2025).
laryngeal carcinoma (2 papers, 2022 to 2024). Carcinoma that arises from the laryngeal epithelium. "For example, it has been regularly reported that laryngeal cancer tissues differentially express certain genes, including EMP1, HOXB9, DPY19L2P1, MMP1, and KLHDC7B, representing independent prognosis predictor genes of laryngeal cancer." (PMID 39452555, 2024).
renal carcinoma (2 papers, 2016 to 2021). A carcinoma arising from the epithelium of the renal parenchyma or the renal pelvis. "We found that the expression of HOXB9 in renal carcinoma patients was lower than that in normal people." (PMID 34306077, 2021). "This miR-192-mediated anti-angiogenic effect was significantly reduced following the rescue of EGR1 and/or HOXB9 levels by lentiviral transduction in these renal cancer cells." (PMID 27041221, 2016). "To assess the therapeutic effect of miR-192 in renal cancer, we injected A498 renal cancer cells expressing an EV or both EGR1 and HOXB9 (A498-EV and A498-EGR1+HOXB9, respectively) into the subcapsular space in the kidneys of mice." (PMID 27041221, 2016).
Arboleda-Tham Syndrome (1 paper, 2022). "The third spans HOXB9 and is hypermethylated in Arboleda-Tham Syndrome patients relative to controls." (PMID 36064314, 2022).
Azoospermia (1 paper, 2023). Absence of any measurable level of sperm,whereby spermatozoa cannot be observed even after centrifugation of the semen pellet. "In the man with azoospermia, we found elevated E2F1 and HOXB9 gene expressions when compared with his brother, suggesting that the increased RNA expression of these genes could influence sperm production." (PMID 37492809, 2023).
benign prostate hyperplasia (1 paper, 2021). "In addition, HOXB9 protein expression was upregulated in PCa tissues, compared with paracancer and benign prostate hyperplasia tissues." (PMID 34247196, 2021).
carcinoma of the lip (1 paper, 2022). "HOXA5, HOXB9, HOXC8, HOXC10, and HOXC11 genes were specific to certain sites of the oral cavity whereas HOXA10 was associated with the development of the carcinoma of the lip and oral cavity." (PMID 35710803, 2022).
cognitive decline (1 paper, 2021). "In the present study, the hypermethylation of probes in the DMRs annotated to HOXB6 was associated with faster rate of cognitive decline, whereas the hypermethylation of probes in the DMRs annotated to HOXB9 was associated with slower rate of cognitive decline." (PMID 34654479, 2021).